RNU6-921P (RNA, U6 small nuclear 921, pseudogene)
Gene: Small nuclear RNA gene on chromosome 14 (68,735,922 to 68,736,028, reverse strand). Ensembl gene ENSG00000207089.
Homologues: Orthologues: chimpanzee U6 (100% identical), dog U6 (82% identical), mouse Gm23013 (80% identical). Paralogues in human: RNU6-10P (93% identical), RNU6-16P (93% identical), RNU6-17P (93% identical), RNU6-18P (93% identical), RNU6-45P (93% identical), RNU6-1 (92% identical), RNU6-12P (92% identical), RNU6-13P (92% identical), RNU6-15P (92% identical), RNU6-2 (92% identical), RNU6-20P (92% identical), RNU6-32P (92% identical), and 1286 more.